WDR5 (WD repeat domain 5)
Description:
Contributes to histone modification. May position the N-terminus of histone H3 for efficient trimethylation at 'Lys-4'. As part of the MLL1/MLL complex it is involved in methylation and dimethylation at 'Lys-4' of histone H3. H3 'Lys-4' methylation represents a specific tag for epigenetic transcriptional activation. As part of the NSL complex it may be involved in acetylation of nucleosomal histone H4 on several lysine residues. May regulate osteoblasts differentiation (By similarity). In association with RBBP5 and ASH2L, stimulates the histone methyltransferase activities of KMT2A, KMT2B, KMT2C, KMT2D, SETD1A and SETD1B.
Synonyms: BIG3; SWD3; CFAP89; BIG-3
Tractability: Small molecule: a structure with a bound ligand is known; a high-quality ligand is known; it has a high-quality binding pocket; it belongs to a druggable protein family. PROTAC: UniProt records ubiquitination sites on it; ubiquitination databases record sites on it; its protein half-life has been measured; a small molecule that binds it is known.
Target class: Reader; Epigenetic regulator; Methyl-lysine/arginine binding protein; WDR domain
Chemical probes: Homer (high quality), LH-168 (high quality), OICR-9429 (high quality)
Gene: Protein-coding gene on chromosome 9 (134,134,346 to 134,159,971, forward strand). Ensembl gene ENSG00000196363.
Subcellular location: Nucleus
Subcellular location (Human Protein Atlas): Nucleoplasm; Principal piece
Pathways (Reactome):
Chromatin organization: CHD6, CHD7, CHD8, CHD9 subfamily; HATs acetylate histones; PKMTs methylate histone lysines; RMTs methylate histone arginines
Gene expression (Transcription): Epigenetic regulation of gene expression by MLL3 and MLL4 complexes; Formation of WDR5-containing histone-modifying complexes; MLL4 and MLL3 complexes regulate expression of PPARG target genes in adipogenesis and hepatic steatosis; RUNX1 regulates genes involved in megakaryocyte differentiation and platelet function
Developmental Biology: Activation of anterior HOX genes in hindbrain development during early embryogenesis; Cardiogenesis; Differentiation of naive CD4+ T cells to T helper 2 cells (Th2 cells)
Signal Transduction: Deactivation of the beta-catenin transactivating complex; Formation of the beta-catenin:TCF transactivating complex
Disease: Loss of Function of KMT2D in MLL4 Complex Formation in Kabuki Syndrome
Immune System: Regulation of PD-L1(CD274) transcription
Metabolism of proteins: Neddylation
Gene Ontology:
Molecular function: histone H3K4me1 reader activity; histone H3Q5ser reader activity; protein binding; histone reader activity; histone H3K4 methyltransferase activity
Biological process: negative regulation of transcription by RNA polymerase II; regulation of cell cycle; regulation of cell division; regulation of DNA-templated transcription; regulation of transcription by RNA polymerase II; regulation of tubulin deacetylation; transcription initiation-coupled chromatin remodeling; positive regulation of DNA-templated transcription; regulation of embryonic development
Cellular component: ATAC complex; histone acetyltransferase complex; histone methyltransferase complex; MLL1 complex; MLL1/2 complex; MLL3/4 complex; NSL complex; nucleoplasm; nucleus; Set1C/COMPASS complex; mitotic spindle
Genetic constraint (gnomAD): Loss-of-function variants: 0 observed, 56.03 expected, observed/expected ratio (o/e) 0, 90% interval 0 to 0.053. The upper end of that interval is the gene's LOEUF score, 0.053, which puts it in group 1 of 6, group 1 being the genes least tolerant of losing a copy. Missense variants: 187 observed, 436.02 expected, observed/expected ratio (o/e) 0.43, 90% interval 0.38 to 0.48. Synonymous variants: 144 observed, 168.13 expected, observed/expected ratio (o/e) 0.86, 90% interval 0.75 to 0.98.
Gene-disease validity (ClinGen):
ClinGen rates the evidence that WDR5 causes each of these diseases.
congenital heart disease (autosomal dominant): Limited. A heart disease that is present at birth.
Homologues: Orthologues: chimpanzee WDR5 (100% identical), guinea pig WDR5 (100% identical), macaque WDR5 (100% identical), mouse Wdr5 (100% identical), rat Wdr5 (100% identical), tropical clawed frog wdr5 (97% identical), zebrafish wdr5 (96% identical), dog WDR5 (92% identical), pig WDR5 (90% identical), Drosophila melanogaster wds (88% identical), Drosophila melanogaster CG10931 (53% identical). Paralogues in human: WDR5B (85% identical), TEP1 (29% identical), POC1A (28% identical), WDR17 (27% identical), POC1B (26% identical), SNRNP40 (24% identical), PAFAH1B1 (23% identical), WDR27 (22% identical), WDR38 (22% identical), AHI1 (21% identical), WDR7 (21% identical), MAPKBP1 (19% identical), and 14 more.
Diseases named in the same sentence as WDR5 in open-access papers:
WDR5 is named in the same sentence as 89 diseases in open-access papers, as found by Europe PMC text mining. Sharing a sentence is not in itself a finding about the gene and the disease. The quoted sentences say what the papers report.
leukemia (29 papers, 2016 to 2026). A malignant (clonal) hematologic disorder, involving hematopoietic stem cells and characterized by the presence of primitive or atypical myeloid or lymphoid cells in the bone marrow and the blood. "Aberrant expression of WDR5 is associated with several cancers, including bladder cancer, leukaemia, and prostate cancer and has been shown to facilitate cell growth, metastasis, and chemoresistance." (PMID 41580526, 2026). "High expression of WDR5 is associated with high risk leukemia; Patients with WDR5 and MLL1 high expression have poor complete remission rate." (PMID 27192115, 2016). "In a nutshell, protein components of the ribosome are encoded by a set of ~80 RPGs, half of which are bound by WDR5 in all cancer cell types profiled to date, including MLLr leukemia cells, Burkitt lymphoma cells, colorectal cancer cells, neuroblastoma cells, and rhabdoid tumor cells." (PMID 38202281, 2024). "Furthermore, WDR5 has been well established as an oncogene and is closely associated with the tumorigenesis and progression of multiple cancers, such as leukaemia and bladder, prostate, and colon cancer." (PMID 34154613, 2021). "The specificity of this low-molecular weight compound for the MLL complex shows the potential for further development of WDR5-dependent enzyme inhibitors associated with MLL-rearranged leukemia or other cancers through inhibition of protein–protein interactions." (PMID 34201935, 2021). "We also found that WDR5 is associated with MLL1 in the leukemia cells." (PMID 27192115, 2016). "This study went a step further to extend the regulatory roles of WDR5 in cancer-immunity cycles from leukemia to solid tumors, and it also expanded the tumor types potentially applied by WDR5-47." (PMID 39201460, 2024). "Although the function of the WDR5/MLL1-H3K4me3 axis has been extended from leukemia to solid tumors such as pancreatic cancer, the relative functions of the WDR5/MLL1-H3K4me3 axis in tumor cells and immune cells in solid tumor is incompletely studied." (PMID 39201460, 2024). "WDR5 has been found to be overexpressed in various cancers, including leukemia, breast cancer, lung cancer, and bladder cancer, suggesting its potential as a therapeutic target for cancer treatment." (PMID 37568727, 2023). "WD repetitive structural domains have biological functions via the epigenetic regulation of gene transcription, and the aberrant expression of WDR5 has been observed in various types of human cancers, including prostate cancer, breast cancer, and leukemia." (PMID 35958927, 2022). "MM-589 selectively inhibited proliferation of MLL1-r leukemia cells with EC50s of ~ 250 nM, significantly more potent than other WDR5 inhibitors." (PMID 33823889, 2021). "This compound also has a picomolar binding affinity and inhibits the proliferation of MYC-induced cancer cells (neuroblastoma and Burkitt’s lymphoma) and MLL1-rearranged leukemia by reducing MYC recruitment to the MYC/WDR5 target gene." (PMID 34201935, 2021). "Recent studies have demonstrated that WDR5 is upregulated in a variety of cancers, including leukaemia, bladder, prostate, and colon cancers, and participates in tumorigenesis and progression." (PMID 34154613, 2021). "It is well known that WDR5 forms the histone H3 lysine 4 methyltransferase complex with mixed lineage leukaemia and promotes RNA polymerase II-dependent transcription activation." (PMID 32541651, 2020). "A direct transcriptional regulation of tumorigenesis by WDR5 on its targets has been reported in leukemia and bladder cancer." (PMID 31752957, 2019). "WDR5 inhibitor OICR-9429 has been successfully used to reduce tumorigenesis of leukemia, pancreatic cancer, and neuroblastoma." (PMID 31752957, 2019).
leukemia (continued). "Other groups have demonstrated similar findings and demonstrated that WDR5 is required for cell survival and proliferation in leukemia, prostate, bladder breast, and pancreatic cancer." (PMID 29925347, 2018). "In summary, we identified that WDR5 is highly expressed in adult ALL and AML, and showed its correlation with high-risk leukemia." (PMID 27192115, 2016). "We also observed the positive correlation of WDR5 expression with these targets in the cohort study of leukemia patients." (PMID 27192115, 2016). "Our finding revealed the WDR5 knockdown results in the proliferation arrest and apoptosis of leukemia cells, and also decreased the expression of its targets through loss of H3K4me3." (PMID 27192115, 2016). "With co-immunoprecipitation assay, we also showed that MLL1 and WDR5 interact in the leukemia cells." (PMID 27192115, 2016). "Therefore, identifying WDR5−MLL1 interaction antagonists such as WDR5-47 has been proposed as a potential therapeutic strategy for MLL-rearranged leukemias." (PMID 39201460, 2024). "However, numerous researches on WDR5 focus on its role as a bridge between the mixed lineage leukemia complex and oncoproteins like MYC." (PMID 38028543, 2023). "WDR5 is also related to the liver infiltration of leukemia cells." (PMID 36483601, 2022). "Knockdown of WDR5 suppresses the proliferation of leukemia cells." (PMID 36483601, 2022). "Here, we describe how WIN site inhibitors act in leukemia cells, reflect on what this tells us about the functions of WDR5, and speculate on what the utility of this new class of inhibitors may be." (PMID 31360909, 2019). "Moreover, recently, an in vivo approach by monobody against WDR5 has been tested in a leukemia background." (PMID 31752957, 2019). "WDR5 has been well-established as an oncogenic factor for MLL-rearranged leukemia." (PMID 30488017, 2018). "We determined the genome-wide occupancy of WDR5 and using chromatin immunoprecipitation followed by deep-sequencing (ChIP-seq) in human RS4;11 ALL and THP-1 AML leukemia cells, we identified 1490 and 515 target genes for WDR5 in RS4;11 and THP-1 cells, respectively." (PMID 27192115, 2016). "However, very little is known about the role of WDR5 in leukemia, despite our growing knowledge about MLL1 fusion proteins and leukemia." (PMID 27192115, 2016). "Next, we explored the effect of WDR5 knockdown in cell growth of leukemia cells." (PMID 27192115, 2016). "Further, we observed that MLL1 and WDR5 are expressed in leukemia cells." (PMID 27192115, 2016). "Here, we found WDR5 expression is increased in leukemia patients." (PMID 27192115, 2016). "However, increasing evidence has shown that WDR5 is upregulated in a range of human cancers and plays a crucial role in cancer cell proliferation, including prostate cancer, breast cancer, leukemia, pancreatic cancer, and neuroblastoma." (PMID 38876301, 2024). "However, the global correlation of WDR5 with H3K4me3 in leukemia cells has yet been determined." (PMID 27192115, 2016). "Notably, WDR5 knockdown dramatically suppress expression of these targets in the leukemia cells." (PMID 27192115, 2016).
leukemia (continued). "WDR5 recruits MLL to the promoters of leukemia-related genes, leading to the activation of these oncogenes and promoting MLL-rearranged leukemia." (PMID 39350229, 2024). "Specifically, WDR5 and RBBP5 of the mixed-lineage leukemia histone methylation complex catalyze histone H3 methylation on lysine K4 (H3K4) that occupies transcription start sites and hydroxyurea (HU)-stalled replication forks." (PMID 37940188, 2024). "MM-102 is also a small molecule inhibitor of WDR5/MLL1 protein-protein interaction that specifically inhibits cell growth and induces apoptosis in leukemia cells harboring MLL1 fusion proteins." (PMID 30841499, 2019). "WDR5 interacts with C/EBPα p30 at genomic regions enriched of histone H3K4 trimethylation marks, and is essential for C/EBPα p30-dependent leukemia cell self-renewal, myeloid differentiation block, and leukemogenesis." (PMID 30488017, 2018). "To confirm the results in human leukemia cells that carry MLL1 translocation, we performed ChIP experiments for MLL1, WDR5 and H3K4me2, using MOLM13 cells that harbor MLL-AF9 translocation." (PMID 27462455, 2016). "However, the oncogenic effect of WDR5 in leukemia remains largely unknown." (PMID 27192115, 2016). "These inhibitors block MLLr leukemia by targeting either transcription cofactors that physically interact with MLL1 (for example, WDR5) or MLL1 fusion proteins (for example, DOT1L and MENIN)." (PMID 27462455, 2016). "In 2019, we reported potent small molecule inhibitors that bind the WIN site of WDR5 with picomolar affinity, specifically block the HMT activity of MLL1 complexes, and selectively kill MLLr leukemia cells in culture—recapitulating much of the behavior of MM-104." (PMID 38202281, 2024). "As an essential component of MLL1, WD repeat-containing protein 5 (WDR5) is critical for its stability and activity through combination with histone H3, and its chromosomal translocation has a close connection with mixed lineage leukemia." (PMID 35402370, 2022). "One of such peptidomimetic, MM-102, effectively decreases the expression of HOXA9 and Meis-1, two critical MLL/WDR5 target genes in MLL fusion protein-driven leukemogenesis, and specifically induces growth inhibition and apoptosis in leukemia cells harboring MLL fusion proteins." (PMID 30488017, 2018). "Through interaction with its C-terminal, WDR5 recruits MLL to regulatory enhancers that are enriched for binding sites for E-twenty-six (ETS) family transcription factors, leading to the activation of leukemogenic genes and leukemia." (PMID 30488017, 2018). "Highly potent and selective antagonists of such interactions have been shown to effectively disrupt the MLL1 complex with WDR5, and Menin and decrease the expression of HoxA9 and Meis‐1, inhibiting proliferation and inducing hematopoietic differentiation in MLL1 leukemia cells." (PMID 28160335, 2017). "Through protein complexes formation with H3K4 methyltransferases, such as SET1A/B and MLL1–4, WDR5 plays an essential role in H3K4me3 and transcriptional activation of target genes involved in pluripotency, development, and cancer, such as MLL-rearranged leukaemia." (PMID 34154613, 2021). "MM-102, MM-401, and MM-589, designed as inhibitors targeting the interaction of WDR5/MLL1, effectively inhibited histone H3K4 methyltransferase activity and reduced oncogenic gene transcription, inhibiting the growth and cell cycle of MLL-rearranged leukemia cells." (PMID 34201935, 2021). "There is no report about WDR5 expression and its correlation with clinical features in leukemia." (PMID 27192115, 2016). "However, it has no report about the WDR5 global binding gene targets in leukemia cells." (PMID 27192115, 2016).